ISG15 (ISG15 ubiquitin like modifier)
Diseases named in the same sentence as ISG15 in open-access papers (continued):
Sharing a sentence is not in itself a finding about the gene and the disease.
parasite infection (5 papers, 2016 to 2025). "In contrast to viral and parasitic infections, which elicit a substantial systemic ISG15 responses characterized by elevated serum levels, ISG15 was undetectable in the serum of mice throughout the whole Ct infection process." (PMID 40627782, 2025). "C57BL/6 mice infected with N67 parasite induced a strong IFN-I response, including increased expression of genes such as Cd40, Isg15, Isg20, Ifit2, Mx1, Mx2, Ddx58, and Usp18 genes, leading to suppression of N67 parasitemia." (PMID 27716849, 2016). "The biological relevance of ISG15 in parasitic infection has been demonstrated." (PMID 34818332, 2021). "In addition, interferon-stimulated gene (ISG) products are a group of newly emerging host restriction factors that can control viral, bacterial, and parasite infection, as exemplified by viperin and ISG15, to name a few (78, –, 81)." (PMID 28130444, 2017). "Interestingly, in contrast to viral and parasitic infections, ISG15 levels were not elevated in the serum of infected mice." (PMID 40627782, 2025).
pneumonia (5 papers, 2017 to 2026). An acute, acute and chronic, or chronic inflammation focally or diffusely affecting the lung parenchyma, caused by an infection in one or both of the lungs (by bacteria, viruses, fungi, or mycoplasma.). "Transcriptomic analysis revealed HIF augmented activation of innate immune response genes, including interferon-stimulated gene 15 (Isg15), in the lung and spleen of mice infected with pneumonia virus of mice (PVM)." (PMID 41945438, 2026). "In an independent set of samples assayed using RT-qPCR, Ifnar2 and the interferon-responsive genes Cxcl11, Ifit1, Irf5 and Isg15 were confirmed to be upregulated during pneumonia." (PMID 28900269, 2017). "Interestingly, in the interferon signaling pathways, Ifnar2 and the interferon-responsive genes Cxcl11, Ifit1, Irf5 and Isg15 were verified to be upregulated during pneumonia, documenting that neutrophils are well able to respond to type I interferon signaling." (PMID 28900269, 2017).
serous ovarian cancer (5 papers, 2018 to 2025). "Both our Kaplan–Meier and Cox survival studies showed that high levels of ISG15 protein expressed by advanced high grade serous ovarian cancer cells are associated with improved patient overall survival." (PMID 30469497, 2018). "In our study, we have shown that ISG15, ISGylation and USP18 are increased in ascites cells when compared with normal ovarian surface epithelial cells and less aggressive high grade serous ovarian cancer cells." (PMID 38939897, 2024). "Darb-Esfanhani and colleagues also demonstrated through immunohistochemical analysis of ISG15 expression on 128 high grade serous ovarian cancer that patients with ISG15-positive tumors had a significantly longer overall survival than patients with ISG15-negative tumors." (PMID 30469497, 2018).
acute kidney injury (4 papers, 2024 to 2025). Sudden and sustained deterioration of the kidney function characterized by decreased glomerular filtration rate, increased serum creatinine or oliguria. "To elucidate the role of ISG15 in the downstream effects contributing to TECs fibrosis, inflammation and renal failure, we have zeroed in on the significance of pyroptosis, a vital innate immune response." (PMID 40462493, 2025). "We hypothesised that the elevated STING‐dependent pyroptosis phenotype is pivotal in the development of renal failure and fibrosis induced by ISG15." (PMID 40462493, 2025). "Furthermore, by analyzing human renal biopsy specimens with rejection and acute kidney injury (AKI), we also identified the abundant presence of Isg15+Mac, as well as the communication between Isg15+Mac and CD8+ T cells via the CCL3-CCR5 ligand-receptor pair." (PMID 41200203, 2025).
Aicardi-Goutières syndrome (4 papers, 2016 to 2022). "We next examined baseline gene expression (qPCR) of archetypal interferon stimulated genes (ISGs) IFI27, USP18, MX1, OASL, IRF7, and MX2, and those ISGs found highly expressed in PBMCs from the type 1 interferonopathy, Aicardi-Goutières syndrome (AGS) patients (IFI27, ISG15, IFI44L, and RSAD2)." (PMID 33746960, 2021).
AIDS (4 papers, 2011 to 2025). A syndrome resulting from the acquired deficiency of cellular immunity caused by the human immunodeficiency virus (HIV). "We suggest that clinical trials be conducted with HIV/AIDS patients to achieve post-ART-mediated minimal detectable virus loads in vivo and subsequent administration of ISG15 in combination with LRA-prodrug PKCMs alternating with ART." (PMID 39810915, 2024).
ataxia telangiectasia (4 papers, 2022 to 2025). Ataxia-telangiectasia is the association of severe combined immunodeficiency (affecting mainly the humoral immune response) with progressive cerebellar ataxia. "Prior reports have noted ISG15 upregulation in models of focal and global cerebral ischemia, CNS viral infection, TBI associated ALS, ataxia-telangiectasia, and to a limited extent in viral and toxic models of demyelinating disease." (PMID 36261842, 2022). "Indeed, in cells with Ataxia Telangiectasia (A-T) or ATM deficiency, elevated ISG15 expression coincides with impaired proteasome-mediated protein degradation, suggesting that ISG15 conjugation interferes with this process." (PMID 40103488, 2025).
chronic hepatitis C (4 papers, 2015 to 2020). "In vivo, in patients with chronic hepatitis C, 2 days after starting pegIFN/ribavirin therapy, a stronger ISG15 inducibility correlates with a milder Treg depletion." (PMID 33376595, 2020). "However, ISG15 displays several immunomodulatory functions: for instance, in chronic hepatitis C (CHC), a persistent expression of ISG15 is responsible for resistance to IFN‐based therapy and contributes to limit inflammation." (PMID 33376595, 2020). "In patients with chronic hepatitis C, the gene expression levels of Rubicon, ISG15, Mx1, and ISG56 were higher than those in non-B, non-C patients." (PMID 32943718, 2020).
depression (4 papers, 2018 to 2025). "Notably, a substantial number of upregulated genes associated with depression were identified, such as Ctss, Ifitm3, H2‐K1, Vim, Bst2, Lag3, Cd74, Isg15, Gbp3, and Cxcl10." (PMID 38946585, 2024). "Moreover, one study has shown a trend towards a greater increase in ISG15 gene expression in peripheral leukocytes of patients with IFN-α-induced depression." (PMID 29040650, 2018). "Regardless of the timepoint of sample collection (pregnancy or postpartum), both ISG15 and RSAD2 were upregulated in the group with postpartum-onset depression compared to the controls (logFC 0.6–0.8, and 1.1 respectively)." (PMID 40473930, 2025). "IL-6 antagonists developed for autoimmune disorders are currently tested in clinical trials for depression (see, for example, ClinicalTrials.gov identifier NCT02473289), and ISG15 inhibition has been proposed as an antiviral strategy and could be repurposed for psychiatric indications." (PMID 29040650, 2018).
Ebola (4 papers, 2016 to 2024). "The mechanisms elucidated in these studies, particularly relating to IFI6's antiviral properties and ISG15's role in immune modulation and viral replication inhibition, offer insights that may be relevant in understanding the specific genetic responses we observed in NHPs infected with Ebola." (PMID 39282474, 2024).
endometrial carcinoma (4 papers, 2008 to 2024). A malignant tumor arising from the epithelium that lines the cavity of the uterine body. "In endometrial carcinomas with high expression of ISG15, the abundance of CD8+ T cells is significantly reduced and their cytotoxic activity is inhibited, increasing the immune escape ability of tumor cells." (PMID 38644421, 2024).
endometritis (4 papers, 2012 to 2022). An acute or chronic, usually bacterial infectious process affecting the endometrium. "A number of studies have reported that IFN-τ alleviates endometritis by inhibiting NF-κB, possibly by inducing the overexpression of multiple ISGs, including ISG15." (PMID 34573559, 2021). "We then silenced and overexpressed ISG15 in the cells to explore the role of the ISGylation modification system in LPS-induced endometritis by regulation of the TLR4/NF-κB signaling pathway." (PMID 34573559, 2021). "The effect of the subclinical uterine infection on the IEIs and ISG15 gene expression must be investigated in future." (PMID 22439976, 2012). "A total of 14 predicted upstream regulators were identified only in healthy cows (P < 0.05), while five unique predicted upstream regulators were identified only in cows after uterine infection, including the inhibition of ISG15 and AIRE, and activation of DUSP1, NFKBIA, and PF4 (P < 0.05)." (PMID 35358206, 2022). "In the present study, the overexpression of ISG15 significantly reduced the mRNA expression levels of IL-1β, IL-6 and IL-8 in gEECs following LPS treatment, while the silencing of ISG15 had the opposite effect, indicating that ISG15 plays a protective role in goat endometritis." (PMID 34573559, 2021). "A total of 12 pregnancy regulated genes were upregulated only in healthy cows and not cows after uterine infection, including CXCL10, ISG15 and TRANK1." (PMID 35358206, 2022). "Furthermore, overexpression of ISG15 decreased p65 phosphorylation and nucleation, while interference with ISG15 expression had the opposite effect, suggesting that ISG15 may play a role in alleviating inflammation by inhibition of the TLR4/NF-κB signaling pathway in LPS-induced endometritis." (PMID 34573559, 2021). "Similarly, expressions of IFNT, ISG15, CXCL10, PPARG, RXRG, SLC2A1, and SLC27A6 proteins were greater and MUC1 was lower in the endometrium of cows without endometritis compared with cows with endometritis (p < 0.05)." (PMID 33920430, 2021).
gastric tumor (4 papers, 2013 to 2025). "In the present study, based on freshly-removed gastric tumors, ISG15 was demonstrated to correlate with irinotecan sensitivity positively." (PMID 23517622, 2013).
Hepatitis (4 papers, 2018 to 2025). Inflammation of the liver. "It was proposed that Adrm1 and Isg15 might work together to induce the overexpression of Ub in ConA-induced hepatitis." (PMID 30177931, 2018). "Non-treated HBs-Tg mice showed higher baseline expression of XBP1s, phos-PERK, CHOP and ISGs (ISG15 and OAS2) in association with mild liver injury (sALT 100–300 U/L) than non-treated WT mice suggesting that HBsAg accumulation triggered UPR activation in association with mild spontaneous hepatitis." (PMID 33979382, 2021). "We previously demonstrated that interferon-stimulated gene 15 protein (ISG15) plays a role in enhancing hepatitis B virus (HBV) and hepatitis C virus (HCV) infections through the ISGylation of the HBV X protein (HBx) and the HCV NS5A protein." (PMID 41249048, 2025). "ISGs that were more highly expressed in hepatocytes in the HBeAg‐positive infection phase than in the hepatitis phases, including IFI44, ISG15, IFI44L, MX1, and OAS3, were not correlated with ALT levels." (PMID 39135698, 2024).
liver diseases (4 papers, 2016 to 2020). "The ISG15 rs1921 variant and ISG15 expression are associated with HBV-related liver diseases." (PMID 27626177, 2016). "Our previous study has also indicated the important role of ISG15 genetic variants and ISG15 serum levels in HBV replication and the progression of HBV-related liver diseases." (PMID 29963243, 2018). "ISG15 serum levels were higher among HBV patients compared to controls (P < 0.0001) and positively associated with HBV-related liver diseases, with highest levels among LC patients." (PMID 27626177, 2016). "In order to explore the influence of ISG15 rs1921 on the clinical outcome of HBV-related liver disease, we compared clinical parameters among patients with different ISG15 rs1921 genotypes (GG, GA and AA)." (PMID 27626177, 2016). "This study investigates the association of Interferon-stimulated gene 15 (ISG15) polymorphisms, ISG15 serum levels and expression with HBV-related liver diseases." (PMID 27626177, 2016). "We have investigated the role of ISG15 variants and ISG15 expression in the progression of HBV-related liver diseases and could show that the non-synonymous ISG15 rs1921 variant, ISG15 levels and ISG15 expression are associated with HBV-related liver diseases." (PMID 27626177, 2016). "In conclusion, our study shows that both the ISG15 rs1921 variant and ISG15 overexpression are associated with HBV-related liver diseases and indicate that ISG15 may be a proviral factor and trigger progression of HBV-related liver diseases." (PMID 27626177, 2016). "Taken together, ISG15 appears to be a proviral factor involved in HBV replication and triggering progression of HBV-related liver diseases." (PMID 27626177, 2016). "However, the functional role of ISG15 in the HBV replication cycle, immune response and clinical progression of HBV-related liver diseases remains poorly understood." (PMID 27626177, 2016). "Although our data indicate that ISG15 over-expression is regulated by HBV infection and may trigger liver disease progression, the study has limitations." (PMID 27626177, 2016). "Therefore, high levels of ISG15, combined with clinical, biochemical and histological analyses may be useful to predict the outcome of HBV-related liver disease and may help to identify HBV-infected individuals positively responding to IFN treatment." (PMID 27626177, 2016). "Due to the study design as a case-control study, ISG15 levels over the course of HBV infection were not assessed longitudinally and the causative effect of ISG15 levels on progression of HBV-related liver diseases could not conclusively be determined." (PMID 27626177, 2016).
oral cancer (4 papers, 2012 to 2023). "In oral cancer, high expressions of ISG15, IFI27, and OASL were associated with low expressions of ATM, the activation of inflamed immune pathways, and increased tumor-infiltrating scores of CD8+ T, natural killer, and dendritic cells." (PMID 37174688, 2023). "In oral cancer, high expressions of ISG15, IFI27, and OASL were found to be associated with low ATM expression (mimicry of ATM inhibition), the activation of inflamed immune pathways, and elevated tumor-infiltrated scores of pDC, NK, and CD8+ T cells." (PMID 37174688, 2023). "The effect of ISG15/IFI27/OASL expression on the configurations of tumor-infiltrated lymphocytes in oral cancer was examined using the cell-type enrichment analysis algorithm xCell." (PMID 37174688, 2023). "Our results revealed that ISG15 is a potential biomarker for detecting lymph node metastases and predicting prognoses of oral cancer." (PMID 33668218, 2021). "Among these ISGs, the high expressions of ISG15, IFI27, and OASL were associated with low ATM expression, the activation of immune pathways, and high tumor-infiltrating scores of DCs, NK, and cytotoxic CD8+ T cells in oral cancer." (PMID 37174688, 2023). "The induction of ISG15, IFI27, and OASL expression by KU55933 was also observed in oral cancer cells CAL27 and derived CDDP-R cancer cells." (PMID 37174688, 2023). "ISG15 is associated with the FGF Signaling pathway and involved in protein metabolism and modification and has been associated at the protein and transcriptomic levels in oral cancer and was once associated with ESCC, suggesting that inhibition of ISG15 may be beneficial in treatment." (PMID 22280838, 2012).
pancreatic adenocarcinoma (4 papers, 2008 to 2025). "Furthermore, in pancreatic adenocarcinoma, peripheral blood ISG15 has also been validated as a potential diagnostic biomarker of cancer patients when compared to healthy controls." (PMID 35864381, 2022). "ISG15 expression is significantly associated with different pathological stages in several cancers, including KIRC, PAAD (pancreatic adenocarcinoma), and SKCM (skin cutaneous melanoma), suggesting a potential role of ISG15 expression levels in dictating pathological progression." (PMID 40208307, 2025).
renal cell carcinoma (4 papers, 2023 to 2025). "A recent study showed that ISG15 can promote proliferation and metastasis through IL6/JAK2/STAT3 signaling in renal cell carcinoma." (PMID 40874680, 2025). "ISG15 is also involved in Listeria-based vaccine-induced interferon-γ and CD8+ T-cell responses in mouse models of renal cell carcinoma." (PMID 37174688, 2023).
sarcoma (4 papers, 2020 to 2025). A usually aggressive malignant neoplasm of the soft tissue or bone. "ISG15 expression was determined, both at mRNA and protein levels, in a panel of sarcoma cell lines: INT-SFT, IEC139, 93T449, CP0024, AA, HT1080, ICP059, ICP060 and SW982." (PMID 35864381, 2022). "ISG15 and IF16 are directly linked together but through PCNA and then through CCND1 they connect indirectly to the common to all sarcomas’ major hubs FGF2 and IL-6." (PMID 34359782, 2021). "In summary, here we demonstrate that ISG15, NUP50, PTTG1, SERPINE1, and TSR1 are highly expressed in sarcoma tissues and associated with sarcoma metastasis and poor prognosis." (PMID 33123466, 2020). "Upon surveying the available data for LGG (brain lower grade glioma), HNSC, KIRC, SARC (sarcoma), LIHC (liver hepatocellular carcinoma), UCEC, and LUSC (lung squamous cell carcinoma), the expression of ISG15 exhibited a positive correlation with ISG15 loss." (PMID 40208307, 2025). "Similarly, INT-SFT showed 4.9- to 33.3-fold more ISG15 protein, when compared to other sarcoma subtypes, but only 1.98-fold more when compared to IEC139." (PMID 35864381, 2022). "ISG15 gene expression levels were significantly higher, in INT-SFT cell line followed by IEC139 (both M-SFT) against other sarcoma subtypes." (PMID 35864381, 2022). "The results of qRT-PCR suggested that ISG15, NUP50, PTTG1, SERPINE1, and TSR1 were highly expressed in sarcoma tissues." (PMID 33123466, 2020). "In sarcoma, a recent bioinformatics study into Ewing sarcoma, comparing tumour samples versus non-cancerous samples, identified ISG15 as one of the hub genes in a protein–protein interaction network (PPI)." (PMID 35864381, 2022). "In sarcoma patients, ISG15 expression is up-regulated in tumour tissue compared to normal tissue, and its expression was included in a metastasis-related genetic signature for poor prognosis." (PMID 35864381, 2022). "To validate whether ISG15, NUP50, PTTG1, SERPINE1, and TSR1 are differentially expressed in sarcoma tissues, we experimentally validated their expression in the tissues of 10 sarcoma patients." (PMID 33123466, 2020). "Of note, ISG15 appeared to be differentially overexpressed in two sarcoma datasets (Tumor Sarcoma Mesenchymal—Boshoff—96 and Tumor Sarcoma—Filion—137) versus a normal tissue repository (Normal Various (GNF)—Su—158), supporting potential interest of ISG15 expression in sarcoma." (PMID 35864381, 2022). "Taken together, results of these experiments suggest that high expression levels of ISG15, NUP50, PTTG1, SERPINE1, and TSR1 exert a positive regulatory effect on metastasis, suggesting poor prognosis, and that Tanespimycin may effectively treat LMS sarcoma subtype." (PMID 33123466, 2020).
Stroke (4 papers, 2023 to 2025). Sudden impairment of blood flow to a part of the brain due to occlusion or rupture of an artery to the brain. "Stroke increased the mRNA expression of PLIN2 and ISG15, one of the typical type I IFN responsive genes, suggesting that the molecular machinery related to lipid droplet biogenesis was activated after stroke in the human brain too." (PMID 36541061, 2023).